MYC (MYC proto-oncogene, bHLH transcription factor)
Diseases named in the same sentence as MYC in open-access papers (continued):
Sharing a sentence is not in itself a finding about the gene and the disease.
lymphoma (continued). "Consistent with inhibition of MYC and HIF1α, administration of echinomycin inhibited growth of lung adenocarcinoma xenograft and a syngeneic lymphoma model in mice." (PMID 33572152, 2021). "Double- and triple-hit lymphomas are now defined as “high-grade B-cell lymphoma (HGBCL) with rearrangements of MYC and BCL2 and/or BCL6”, an entity separate from DLBCL in the 2016 revision of the World Health Organization lymphoma classification." (PMID 34945817, 2021). "High-grade lymphomas with MYC and BCL 2 translocation (double hit) represent about 5% of all large B cell lymphomas with CNS involvement at diagnosis or relapse approaching 50%." (PMID 34513408, 2021). "Compared to ND fractioned B- and T-lymphocyte subsets in peripheral blood, all canine lymphoma cell lines showed higher levels of MYC and PRMT5 protein." (PMID 33989303, 2021). "In a more adaptive approach, HSCs derived from fetal liver cells were transduced with either mutant or wild-type MYC-expressing retroviral vectors to produce lymphoma." (PMID 34372899, 2021). "Consistently, we also reported CYCLON as being, at least partly, a MYC downstream target in lymphoma cell lines." (PMID 34885010, 2021). "Total number of hypomethylated DMRs was similar between MYC;Dnmt3b+/+ and MYC;Dnmt3bCI/CI lymphomas (∼23,000) suggesting that Dnmt3bCI protein restored at least some Dnmt3b functions lost in MYC;Dnmt3bΔ/Δ lymphomas." (PMID 33450231, 2021). "Differences in growth suggest that every clone represents a unique lymphoma model despite sharing c-MYC overexpression as main driver." (PMID 34638774, 2021). "In mouse models, the combination of MYC with CBX7 overexpression resulted in a faster lymphoma development." (PMID 35008680, 2021). "In fact, poor clinical outcomes for lymphomas patients with co-expression of MYC and BCL2 were previously reported." (PMID 33718209, 2021). "Only DNAi 5T, however, modulated lymphoma toxicity with correlating changes in MYC transcription in the RAJI cell line and passed the CA46 exon test." (PMID 34577013, 2021). "BCL6 and MYC rearrangements simultaneously occurred in case 8, which was diagnosed as “double hit” lymphoma." (PMID 34267187, 2021). "MYC promotes the uptake of essential amino acids (i.e., glutamine) through SLC7A5/SLC43A1 in lymphoma cells, which in turn stimulate the MYC translation and tumorigenesis." (PMID 34692527, 2021). "We would expect, therefore, that disrupting the MYC–HCF-1 interaction would have a significant impact on the ability of Ramos lymphoma cells to establish and maintain tumors in vivo." (PMID 33416496, 2021). "Preclinical models also showed that combining BETi with the BH3 mimetic, BCL-2 antagonist venetoclax was beneficial in MYC-overexpressing lymphoma cells." (PMID 35008680, 2021). "Consistently, the T58A mutation has previously been reported to uncouple the role of MYC as an inducer of cell growth and proliferation from its induction of apoptosis during lymphoma onset." (PMID 34885204, 2021). "This approach was used to map rDNA contacts at better resolution (5 kb or less) using a MYC-driven lymphoma model or HEK293T cells." (PMID 34531902, 2021). "Aiming for mice that develop primary h/mCD22+ lymphoma, we chose from various possible oncogenes the B cell specific overexpression of c-MYC that leads to spontaneous aggressive lymphoma." (PMID 34638774, 2021).
lymphoma (continued). "In the MYC-driven lymphoma model, during the cellular transition from premalignancy to malignancy, there is a correlation between interactions of associated genes with the rDNA and transcriptional repression." (PMID 34531902, 2021). "Knock-out of SCRIB delayed expansion of B cells in the development of MYC-mediated lymphoma development." (PMID 33803371, 2021). "We find that this type of therapy is highly effective against aggressive and MYC+/BCL2+ lymphoma cells in vitro and in vivo." (PMID 33562682, 2021). "This is essential since double-hit lymphomas with aberrant expression of MYC and BCL2 has dismal outcome." (PMID 33737576, 2021). "Investigation of Dinaciclib-mediated inhibition of CDK9 in aggressive MYC-induced lymphomas demonstrated the remarkable effectiveness of CDK9 inhibitors." (PMID 34372899, 2021). "It was soon recognized that BCL2 was involved in the regulation of apoptosis and that it cooperated with the MYC oncogene in lymphoma pathogenesis." (PMID 34576319, 2021). "Dysregulation of MYC in leukemia and lymphoma, which mostly leads to overexpression, is mainly due to gene amplification, chromosomal translocations, aberrant transcription, and increased stability of mRNA and protein." (PMID 34372899, 2021). "We and others have shown the feasibility of eIF4A inhibitors against a range of cancers including leukemia, non-Hodgkin’s lymphoma—especially MYC+/BCL2+ lymphomas, and perhaps more modestly against pancreatic cancer." (PMID 33562682, 2021). "The transloactions involving MYC gene at chromosome 8 are more found in lymphoma comparted to leukemia." (PMID 34372899, 2021). "Overexpression of MCL-1 greatly accelerates the development of lymphoma driven by the oncogene c-MYC." (PMID 33883020, 2021). "CUDC-907 has been tested in clinical trials on various hematological cancers, including relapsed or refractory lymphoma, multiple myeloma, MYC-altered DLBCL, and CLL." (PMID 34372899, 2021). "The decreased IL-12/IL-10 ratio in DCs from untreated tumor-bearing mice is likely a consequence of IFN-γ suppression, which occurs in the microenvironment of growing λ-MYC lymphomas." (PMID 33141285, 2021). "For example, several of our top genes showed a tight SNV clustering pattern associated with elevated expression, including MYC, BCL2, PIM1 and IGLL5 in lymphoma." (PMID 33554123, 2021). "Sixty-four (45.4%) tumors showed a MYC rearrangement; 29 (20.57%) samples thereof had an additional BCL2 rearrangement (hence belonging to the DHL category); one lymphoma sample revealed translocations in MYC, BCL2, and BCL6 (THL)." (PMID 34830747, 2021). "In this complex pathway, high MYC level downregulates mir-150 expression to protect the oncogenic and lymphoma related MYB from mir-150-mediated repression." (PMID 33544339, 2021). "BFL-1/A1 is overexpressed in therapy-resistant lymphoma cell lines, and its expression enhances the survival of c-MYC-dependent B-cell lymphomas and EBV LMP1 protein-expressing Burkitt lymphoma." (PMID 34576319, 2021). "Like most human cancer models driven by MYC, the development of lymphomas in Eμ-myc mice involves the subversion of normal signaling pathways and the acquisition of secondary driver mutations, resulting in clonal expansion of tumor cells." (PMID 33651821, 2021). "This puzzle was investigated in osteosarcoma and lymphoma where blockade of MYC successfully remove the complete tumor." (PMID 33958005, 2021). "It is interesting to note that lymphomas with MYC overexpression induce cytoprotective autophagy to escape stressful conditions." (PMID 34782660, 2021). "At initial diagnosis, 70% of patients had Ann Arbor stage III/IV disease, 56% had non‐germinal center B‐cell‐like type DLBCL, and 42% had double‐expressor lymphoma (MYC and BCL2 expression)." (PMID 34105893, 2021). "The optimized DNAi 5T, indeed, mediated inhibition of lymphoma cell viability in correlation with MYC downregulation through apparent promoter G4 stabilization." (PMID 34577013, 2021).
lymphoma (continued). "Next, we used WGBS to determine methylation patterns in MYC;Dnmt3b+/+, MYC;Dnmt3bCI/CI, and MYC;Dnmt3bΔ/Δ lymphomas (two samples per genetic group)." (PMID 33450231, 2021). "In a previous study, PI 18:0/18:2 and PI 18:0/20:3 were mostly increased in MYC gene-activated lymphoma, compared to inactivated lymphoma." (PMID 34439333, 2021). "Here, mice transplanted with haematological cells expressing these MYC mutants succumbed to lymphomas more rapidly than their wild-type counterparts." (PMID 33799592, 2021). "Our data demonstrated a new mechanism by which echinomycin simultaneously targets MYC and HIF1α for degradation to inhibit growth of lung cancer and lymphoma." (PMID 33572152, 2021). "MYC overexpression also affects lymphoma immunophenotype, transcriptional characteristics and metabolic conditions." (PMID 35071240, 2021). "Although the loss of one MCL-1 allele does not significantly impair the survival of normal B lymphocyte-like cells, it almost completely abrogates the development of MYC-driven lymphomas." (PMID 33883020, 2021). "In such cells, transition from a normal to a lymphoma phenotype is directly dependent on the MYC expression level, without a requirement for secondary events that are normally required during MYC-driven oncogenic transformation." (PMID 34885204, 2021). "NPM-ALK–driven lymphoma in mice is dependent on MYC signaling and epigenomic reprogramming via DNA methyltransferases, resulting in heterogenous DNA methylation signatures reminiscent of human lymphoma." (PMID 33310759, 2021). "The critical role of MCL1 during MYC-driven lymphomagenesis and for the continued survival of lymphoma cells has been repeatedly demonstrated." (PMID 34576319, 2021). "Meanwhile, in an MYC lymphoma mouse model and in vitro cell lines, MYC was shown to transcriptionally upregulate PD-L1 and CD47 in tumor cells." (PMID 33917037, 2021). "In lymphoma cells treated with BETi plus HDACi, the BETi RVX2135 sensitizes MYC-overexpressing lymphoma cells, triggering the re-expression of HDAC-silenced genes." (PMID 33801599, 2021). "Three independent clinical trials investigated the effect of different CD19 targeting CAR T products in DLBCL and reported outcomes of patients with MYC overexpressing lymphomas as subgroups." (PMID 33092116, 2020). "GSEA data showed enriched MYC pathway-related genes in MYCT58A lymphoma cells compared with MYCWT lymphoma cells." (PMID 33298911, 2020). "In the context of lymphomas with MYC overexpression, there is a tight competition for vital nutrients with the neighboring immune cells, and a negative impact of specific by-products generated by the MYC-expressing lymphoma cells." (PMID 33092116, 2020). "Our results demonstrate that the activation of c-MYC in lymphoma cells drives immune suppression through the downregulation of exosomal miRNA-7e-5p and activation of FAS-mediated apoptosis in macrophages." (PMID 33168041, 2020). "In agreement, another preclinical study demonstrated that the combination of statins with venetoclax was cytotoxic to DLBCL, CLL, and AML cells and reduced lymphoma burden in a syngeneic mouse model of BCL-2/MYC driven “double hit” lymphoma." (PMID 32183335, 2020). "We found that TRIB3 interacts with MYC to suppress E3 ubiquitin ligase UBE3B-mediated MYC ubiquitination and degradation, which causes high proliferation and self-renewal of lymphoma cells." (PMID 33298911, 2020). "Remarkably, the alterations that trigger MYC overexpression differ between leukemia and lymphoma cells." (PMID 32102485, 2020). "MYC-activated lncRNA-FIRRE facilitates lymphoma progression through regulation of the nuclear translocation of β-catenin to activate Wnt/β-catenin pathway." (PMID 33148302, 2020). "In the specific case of B lymphocytes, the use of transgenic mice overexpressing MYC revealed a developmental blockade at the B cell stage, before the onset of lymphoma." (PMID 32102485, 2020).
lymphoma (continued). "More importantly, some of them are induced and regulated by MYC, a well-known transcription factor and is considered to be the major driving force in lymphoma development." (PMID 33148302, 2020). "The results described here establish a clinically relevant mouse model of double-expressor lymphoma by targeting constitutive expression of c-MYC and BCL2." (PMID 32695674, 2020). "TGR-1202 selectively inhibits PI3Kδ in lymphoma, leading to decreased MYC protein levels and induced lymphoma cell death." (PMID 33092116, 2020). "DLBCL associated with translocation of MYC and BCL2 and/or BCL6 (double-hit or triple-hit lymphomas) needs to be investigated in the context of high risk for CNS relapse of primary breast DLBCL." (PMID 32781541, 2020). "Our results show mutations at loop anchors are associated with upregulation of the cancer driver genes BCL2 and MYC in malignant lymphoma thus pointing to a possible new mechanism for their dysregulation via alteration of insulator loops." (PMID 32216817, 2020). "DEL is defined as positivity of both MYC and BCL2 in lymphoma tissues by IHC (Cut-off values: 40–50% for MYC, 50–70% for BCL2)." (PMID 32664092, 2020). "MYC has been described as a proto-oncogene that is closely involved in many cancers, including leukemia and lymphoma." (PMID 32102485, 2020). "Overexpression of MCL1 has been shown to potentiate c-MYC induced lymphoma development via suppressing c-MYC driven apoptosis." (PMID 33187130, 2020). "Mice overexpressing MCL-1 in hematopoietic stem/progenitor cells are prone to malignant transformation, particularly (MYC-driven) lymphomas of the B-cell lineage." (PMID 33308268, 2020). "Here, the authors show that a member of the pseudokinase family, tribbles homologue 3 (TRIB3), interacts with c-MYC to suppress c-MYC ubiquitination and degradation, leading to increased proliferation and self-renewal of lymphoma cells." (PMID 33298911, 2020). "DLBCL cases with dual rearrangement of MYC and BCL2 and/or BCL6, frequently named “double-hit” lymphomas, are associated with significantly shorter survival and have been reclassified as a new group of lymphomas by the World Health Organization." (PMID 33087075, 2020). "In 26 (72%) of the 36 cases, MYC amp was identified at the time of initial diagnosis of aggressive lymphoma." (PMID 31932576, 2020). "The ‘DH’ lymphomas are defined as a chromosomal breakpoint affecting the MYC/8q24 and another recurrent genetic abnormality, mainly involving BCL2, BCL6, BCL3 or other genes." (PMID 32459397, 2020). "By examining the endogenous interactions with Co-IP, we found that MYC, UBE3B, and MAX (also known as MYC-associated factor X) formed the heterotrimer in lymphoma cells." (PMID 33298911, 2020). "Our study highlights a key mechanism for controlling MYC expression and a potential therapeutic option for treating lymphomas with high TRIB3-MYC expression." (PMID 33298911, 2020). "MAX expression in ALK-positive ALCL patients was significantly lower than in PTCL-NOS in the GSE65823 dataset, whereas MYC mRNA levels were comparable among these lymphomas." (PMID 32587329, 2020). "Such lymphoma derived MYC mutants (T58A, P57S) have been shown to increase the half-life of MYC protein from 30 to 110 min, and also confer increased transforming capacity, but are defective in promoting apoptosis due to failure to activate BIM." (PMID 31844144, 2020). "In the 2017 WHO lymphoma classification, MYC/BCL6-DH DLBCL are included in the double-hit category, without any distinction from those with MYC/BCL2/BCL6-TH or MYC/BCL2-DH." (PMID 31844144, 2020). "Combined ICB with anti-CTLA-4 and anti-PD-1 mAb protected 18% to 30% of λ-MYC mice from lymphomas for at least 200 days." (PMID 32165639, 2020). "MYC/BCL2 double‐hit lymphomas tend to demonstrate themselves with advanced stage and poor prognostic parameters including extranodal infiltration and elevated LDH,10, 27 and a high FLIPI score." (PMID 32459397, 2020).
lymphoma (continued). "Several tumor types show heterogeneous dependence on MCL-1 including breast, lung, multiple myeloma (MM) and MYC-driven lymphomas." (PMID 32335811, 2020). "Concomitantly inhibitory action of both EZH2 and HDAC3 promoted transcriptional and epigenetic MYC-mediated repression of miR-29, resulting in down-regulation of miR-29 target pro-apoptotic genes and lymphoma growth suppression in vitro and in vivo." (PMID 32549409, 2020). "The transcription factor MYC is deregulated in almost all human cancers, especially in aggressive lymphomas, through chromosomal translocation, amplification, and transcription hyperactivation." (PMID 33298911, 2020). "Since patients with MYC overexpressing lymphomas face a significant dismal prognosis after treatment with standard immunochemotherapy, understanding the role of MYC in regulating the anti-tumor immune response is highly relevant." (PMID 33092116, 2020). "Whereas systemic DLBCL with co-expression of c-Myc and Bcl-2 (double-expressor) and/or co-rearrangement of MYC and BCL2 and/or BCL6 (double or triple hit lymphoma) has been associated with a worse prognosis, the findings were inconclusive for PCNS DLBCL." (PMID 33322508, 2020). "Many features of canine diffuse large B-cell lymphoma resemble the ABC form of human DLBCL, including constitutive activation of the NF-kB pathway, and almost universal presence of double expressing MYC/BCL2 lymphomas." (PMID 32038991, 2020). "The shift towards pro-survival signaling in MYC-transformed lymphoma cells can, therefore, contribute to immunochemotherapy resistance, including reduced sensitivity for T cell and NK cell-mediated apoptosis." (PMID 33092116, 2020). "In this review, we give an overview of lncRNAs that have been recognized as critical in the context of activated c-MYC in leukemia and lymphoma, describe their mechanism of action and their effect on transcriptional reprogramming in cancer cells." (PMID 33134177, 2020). "In FL and DLBCL, the translocation and activation of c-MYC and B-cell lymphoma 2 (BCl2) is regarded as “double-hit lymphoma” because of the poor survival of patients with this pattern of genetic alteration." (PMID 33168041, 2020). "Using transgenic mice with Trib3 deletion in different cell lineages, we found that TRIB3 participated in MYC-driven lymphoma tumorigenesis and pathogenesis." (PMID 33298911, 2020). "Binding of MYC near the promoters of Snhg12, Mir17hg is readily detected and increases in B cells from the pre-lymphomatous and the fully malignant stage (lymphoma)." (PMID 33134177, 2020). "In this review, we refer to both SH, DH or TH HGBL and DE lymphomas with “MYC overexpression”, since this eventually all results in high MYC protein expression." (PMID 33092116, 2020). "Targeting MYC, especially in combination with traditional therapies, is considered an attractive therapeutic strategy for lymphomas and other MYC-driven cancers." (PMID 33298911, 2020). "FL can also transform into a composite lymphoma, combining a HGBL with BCL2 and/or BCL6 and MYC rearrangements, and a B-ALL characterized by a loss of maturity markers, such as CD20 and surface immunoglobulins." (PMID 32713346, 2020). "Intriguingly, in MYC driven lymphomas, RiBi is in excess of requirements for the accelerated proliferation as rescuing apoptotic cell death induce by a 30–40% reduction by Pol I transcription inhibition restores a normal proliferative rate." (PMID 31973211, 2020). "As regards DH lymphomas, MYC and BCL2 rearrangements frequently trigger the corresponding protein overexpression, characterizing a specific group called DPE lymphomas, clinically featuring rapid progression and poor outcome." (PMID 31940809, 2020). "Dog cancers of all types, including lymphomas, frequently have gain of part or all of chromosome 13, which carries MYC and KIT." (PMID 32038991, 2020).